APOB (apolipoprotein B)
Diseases named in the same sentence as APOB in open-access papers (continued):
Sharing a sentence is not in itself a finding about the gene and the disease.
dyslipidemia (continued). "Both ApoB and non-HDL-C are also recommended to improve ASCVD risk assessment, particularly in situations where discordance between these measures and LDL-C may occur (e.g. diabetes mellitus, obesity, metabolic syndrome, high TGs, and very low LDL-C levels)." (PMID 33941192, 2021). "The ApoB/ApoA-I ratio, ApoB, blood pressure levels, WC, BMI, LDL-C, FG, FIns, TG, TC, HOMA2-IR, the prevalence of MetS, AH, and dyslipidemia were all significantly higher but HDL-C and ApoA-I levels were significantly lower in men than in women (all P < .0001)." (PMID 24949011, 2014). "Among patients with clinically manifest vascular disease, the metabolic syndrome and elevated TG levels are common, and the results of the present study show that rs964184 is associated with plasma TG in these patients, as well as with HDL-c, nonHDL-c and apoB." (PMID 24979386, 2014). "Given the heterogeneity of dyslipidemia in diabetes, non-HDL-C and apolipoprotein B (apoB) have emerged as superior markers for assessing atherogenic burden." (PMID 41968323, 2026). "Their benefits extend across TG levels and should remain first-line pharmacologic therapy in patients with mixed dyslipidemia, elevated LDL-C, non-HDL-C or ApoB levels." (PMID 41012446, 2025). "The status of being metabolically at-risk, overweight/obesity, and high SF increased the ORs for hyperuricemia and dyslipidemia (including TG, TC, LDL-C, non-HDL-C, and apoB)." (PMID 33659229, 2021). "Significant associations were observed for high SF with diabetes in MANW and MAO groups, with unfavorable LDL-C in MHNW and MHO groups, and with other dyslipidemia components (including TG, TC, non-HDL-C, and apoB) and hyperuricemia for all phenotypes." (PMID 33659229, 2021). "The 2019 European Society of Cardiology/European Atherosclerosis Society (ESC/EAS) Guidelines for the management of dyslipidemias support the evaluation and consideration of non-HDL-C and apoB as secondary targets for lipid control." (PMID 34677405, 2021). "Compared with individuals without high SF, subjects with high SF exhibited an increased prevalence of hyperuricemia and dyslipidemia (regarding TC, TG, non-HDL-C, and apoB) for all body phenotypes." (PMID 33659229, 2021). "In persons with hypertriglyceridaemia, type 2 diabetes, or metabolic syndrome and in obese persons, measurements of LDL-C are less accurate for methodological reasons, which is why non-HDL-C or apoB measurements are recommended." (PMID 34851955, 2021). "In individuals with T2DM and mixed dyslipidemia, alirocumab significantly reduced LDL-C, non-HDL-C, ApoB, Lp(a), and LDL particle number, and significantly increased HDL-C, compared with usual care overall." (PMID 32035487, 2020). "The prevalence of dyslipidemia (including in TC, TG, LDL-C and apoB) increased with increasing OSA severity in non-obese subjects and those <55 years of age not in obese or older subjects (except apoA-I in older subjects)." (PMID 28134311, 2017). "Overall, the findings of the current study support prior study results, showing that treatment with ERN/LRPT and ERN (without LRPT) produces somewhat comparable reductions in apoB, LDL-C and non-HDL-C in patients with dyslipidemia." (PMID 27405296, 2016). "Growing evidence indicates that during treatment of dyslipidemia, CVD events correlate more strongly with levels of apoB and non-HDL-C." (PMID 26087958, 2015). "Non-HDL-C determination includes cholesterol from atherogenic lipoproteins not captured by Friedewald's estimation, such as apoB-carrying remnants not belonging to LDL or IDL and often found in diabetic patients and/or in subjects with metabolic syndrome." (PMID 21356116, 2011). "Obicetrapib significantly reduced key dyslipidemia biomarkers including low density lipoprotein cholesterol (LDL-C), Apolipoprotein B (Apo B), and non-high-density lipoprotein cholesterol (non-HDL-C) while increasing high-density lipoprotein cholesterol (HDL-C)." (PMID 39150671, 2024).
dyslipidemia (continued). "For such individuals, the ESC/EAS 2019 dyslipidemia guidelines recommend an LDL-C goal of < 1.4 mmol/L, at least a 50% reduction from baseline in LDL-C, and secondary goals of non-HDL-C < 2.2 mmol/L and ApoB < 65 mg/dL." (PMID 33941192, 2021). "Our results confirm the equivalence of both measurements in their capacity to rank diabetic patients with a broad spectrum of lipid values, from normal to frank dyslipidemia with elevated atherogenic cholesterol (non-HDL-C) and/or atherogenic particles number (apoB)." (PMID 21356116, 2011). "Because apoB and LDLC tests do not quantify the same measurand, the discordance of test results is inevitable, especially in people with predominant small cholesterol-depleted LDL particles such as in those with hypertriglyceridemia, diabetes, obesity, and metabolic syndrome." (PMID 34955672, 2022). "Moreover, the 2019 European Society of Cardiology/European Atherosclerosis Society (ESC/EAS) guidelines for the management of dyslipidemias have defined secondary goals for both non-HDL-C and ApoB to help guide lipid-lowering therapy adjustments after the achievement of an LDL-C goal." (PMID 33941192, 2021). "Individuals with mixed dyslipidemia may also have an elevated number of small, dense low-density lipoprotein (LDL) particles, as reflected by higher levels of ApoB-100 (ApoB); however, these individuals may not necessarily have elevated LDL cholesterol (LDL-C) levels." (PMID 32035487, 2020). "The impact of non-fasting state on clinical decision making in the identification of dyslipidemias is similar for both non-HDL-C and TG/HDL-C, although non-HDL-C better reveals abnormalities in lipid metabolism, covering all atherogenic particles containing ApoB." (PMID 29927973, 2018).
diabetes (421 papers, 2006 to 2026). "Independent factors: older age, diabetes, higher ApoB/ApoA ratio, longer disease duration (risk factors), higher HDL-C (protective factor, all p < 0.05)." (PMID 41929591, 2026). "Extending our previous observations, we found that the excess of CLD among APOB variant carriers was independent from age, sex, BMI, diabetes, alcohol intake and PNPLA3 genotype status." (PMID 41549954, 2026). "In sensitivity analyses, we found that diabetes increased the risk of new‐onset CLD events by 4.8‐fold in APOB carriers, and this effect was further amplified by the presence of concurrent obesity." (PMID 41549954, 2026). "Using UK Biobank data, we analysed 241 APOB loss‐of‐function (LoF) carriers and 410 721 non‐carriers, stratified by steatogenic risk factors, including age, sex, diabetes, BMI, alcohol intake and the PNPLA3‐rs738409 genotype." (PMID 41549954, 2026). "Populations with high LDL-C/ApoB often have diabetes, hypertension, obesity, and other independent risk factors for CKD, which can damage the renal tubules and potentially affect KIM-1 expression." (PMID 41430991, 2025). "The PAF of 20‐year ASCVD incidence was 20.3% (95% CI, 9.3–29.9) for apoB levels exceeding 100 mg/dL and 21.3% (95% CI, 11.7–28.9) for traditional modifiable risk factors (smoking, physical inactivity, hypertension, diabetes, obesity)." (PMID 40386959, 2025). "In a sensitivity model that additionally included age, diabetes, and albumin, muscle density, muscle volume, hypertension, and ApoB remained significant variables associated with CVEs, whereas HbA1c lost significance." (PMID 41299285, 2025). "In comparison to other traditional risk factors such as smoking, arterial hypertension, and diabetes mellitus, ApoB and the ApoB/ApoA1 ratio have demonstrated strong and independent associations with the risk of acute myocardial infarction." (PMID 38393015, 2024). "Individuals with type 2 diabetes mellitus and albuminuria are reported to exhibit increased serum apoB100 levels, suggesting a potential association between ApoB concentrations and the presence of diabetic nephropathy." (PMID 38393015, 2024). "Patients with diabetes who received 240 mL of cranberry juice for 12 weeks showed lower serum glucose levels and improved levels of cardiovascular risk markers (apoB, apoA-1, and Paraoxonase-1)." (PMID 38752013, 2024). "AMI worldwide is associated with nine modifiable risk factors (ApoB/ApoA1 ratio, hypertension, diabetes, abdominal obesity, smoking, psychosocial factors, poor diet, regular alcohol consumption and lack of regular physical activity)." (PMID 38478535, 2024). "Intriguingly, there was a dichotomy in the association of WAT IL-1β-secretion to diabetes risk factors depending on the apoB-group and WAT stimulus." (PMID 37914804, 2023). "Adjusting for WAT NLRP3 and IL1B mRNA and mostly for maximal LPS/ATP-induced IL-1β-secretion attenuated the association of plasma apoB with diabetes risk factors." (PMID 37914804, 2023). "Serum ApoB level was positively associated with diastolic blood pressure (p=.044), the concomitant of arthritis (p=.001), and diabetes (p=.006)." (PMID 34996506, 2022). "After excluding patients with hypertension and diabetes, ApoB was still significantly associated with cognitive function in all the patients." (PMID 36506447, 2022). "There was a significantly greater decrease in both apoB and TG in carriers of the rs12740374 variant with diabetes." (PMID 35113816, 2022). "In our analysis, total adiposity and VAT were associated with higher cardiovascular risk factors, including blood pressure, the frequency of diabetes, apolipoprotein B/A ratio, and MRI-detected vascular brain injury." (PMID 35103790, 2022). "SPX (spexin hormone) and APOB (apolipoprotein B) are a critical proteins plays an important role in obesity associated type 2 diabetes mellitus." (PMID 33902539, 2021).
diabetes (continued). "It is possible that specific environmental and lifestyle factors influence the associations between the APOB rs693 polymorphism and GD, including age, sex, diet, diabetes, smoking, familial history, surgical history, and hypertension." (PMID 33941261, 2021). "We tried to identify the interaction between dietary quality indices and apolipoprotein B Ins/Del and EcoR1 polymorphisms on biochemical and anthropometric factors in patients with type 2 diabetes mellitus (T2DM)." (PMID 34789800, 2021). "In this study, increased and increasing ApoB were found to be independently associated with progression of CKD in diabetes patients until RRT was needed." (PMID 32242489, 2020). "These were used with UAE and derived measures of HDL apoA-I content (apoA-I/HDL-C and apoA-I/HDL-P) in risk models adjusted for gender, age, apoB, diabetes, past CVD history, CRP and GFR." (PMID 30813431, 2019). "Hazard ratios reveal risk with increasing age, gender (males > females), apoB concentration, diabetes, past history of CVD, CRP concentration, and decreasing eGFR." (PMID 30813431, 2019). "Nevertheless, the associations between the ApoB/ApoA-I ratio and pre-diabetes or diabetes risk in women were more obvious than in men." (PMID 28110289, 2017). "Oxidized HDL quartiles were inversely associated with male gender, prevalence of diabetes mellitus, BMI, apoB/apoA-I and hs-CRP, and positively associated with hemodialysis vintage, Kt/V, HDL-C and apoA-I." (PMID 28542510, 2017). "Collectively, the results of this study provide valuable evidence for a better understanding of the ApoB/ApoA-I ratio in detecting pre-diabetes and diabetes risk in the Chinese population, especially in women." (PMID 28110289, 2017). "In women the significant risk factor other than smoking was elevated ApoB/ApoA1 ratio, whilst among male cases BMI ≥ 25.0 and diabetes were associated with an increased risk." (PMID 28666478, 2017). "A recent study investigated further the role of apolipoprotein-B in CVD risk in 267 adolescents with T1DM who had at least 5 years duration of diabetes and an average HbA1c 8.9 ± 1.6%." (PMID 29101482, 2017). "As a consequence, the ratio of ApoB/ApoA-I was positively associated with pre-diabetes and diabetes." (PMID 28110289, 2017). "We found the association between ApoB/ApoA-I ratio and the risk of diabetes was still significant in women after adjusting for conventional factors." (PMID 28110289, 2017). "The ApoB/ApoA-I ratio showed positive associations with the risk of diabetes and pre-diabetes in Chinese women." (PMID 28110289, 2017). "After adjusting for age, SBP, DBP, BMI and other lipid levels, the association between the ApoB/ApoA-I ratio and pre-diabetes was attenuated but still significant in T3 group (RR 2.186, 95% CI 1.376 to 2.842, p<0.01)." (PMID 28110289, 2017). "In women, the risk of pre-diabetes was increased across the tertile of the ApoB/ApoA-I ratio (T2: RR 1.568, 95% CI 1.119 to 2.044, p<0.01; T3: RR 2.221, 95% CI 1.728 to 2.647, p<0.001)." (PMID 28110289, 2017). "After further adjusting for confounding factors, the risk of diabetes in the top tertile of the ApoB/ApoA-I ratio was still 3.65-fold higher than in the bottom tertile (RR 3.651, 95% CI 1.685 to 6.099, p<0.01)." (PMID 28110289, 2017). "As has been observed by others, we found that induction of diabetes in Apoe−/− mice with STZ resulted in an approximately two‐fold increase in apolipoprotein B‐associated plasma cholesterol." (PMID 24920125, 2014). "At present, the American Diabetes Association and the American College of Cardiology have stated that apoB is the test of choice to assess the adequacy of statin treatment and should therefore be introduced into routine clinical practice." (PMID 23359805, 2013). "Both apoB and apoA1 were significantly associated with obesity when age, sex, diastolic blood pressure, homocysteine, diabetes, and insulin resistance were controlled for." (PMID 21159217, 2011).
diabetes (continued). "Future research should determine the association of apoA1 and apoB:apoA1 ratio on cardiovascular outcomes in First Nations peoples with diabetes." (PMID 21159217, 2011). "A score consisting of adiponectin, apolipoprotein B, C-reactive protein and ferritin almost doubled the relative risk of diabetes in the validation cohort (HR per one standard deviation increase 1.88, p = 2.8 e-5)." (PMID 20396381, 2010). "As detailed elsewhere (review, increased ASP is associated with obesity, diabetes and increased fasting plasma cholesterol, triglyceride, apolipoprotein B and NEFA." (PMID 16472384, 2006). "Subgroup analysis among subjects with available apoB/apoA-1 ratio (n=68 435) showed an increased association with aortic stenosis among all groups with elevated glucose, with the highest association observed in those with known diabetes." (PMID 39915078, 2025). "Notably, specific APOB variants impacted diabetes risk through low-density lipoprotein cholesterol levels." (PMID 38201907, 2023). "To explore whether the WAT NLRP3 inflammasome/IL-1β pathway is related to higher diabetes risk factors in subjects with high-apoB, we used partial correlation analysis." (PMID 37914804, 2023). "However, among those with excess BMI or diabetes, associations with higher total cholesterol, ApoB, and IDL and large LDL particles, which were otherwise hazardous among those without such metabolic conditions, appeared inverse." (PMID 36872307, 2023). "Given that the ApoB/ApoA ratio is associated with risk of diabetes and prediabetes, reduction of waist circumference may be a useful strategy in this patient group." (PMID 36673620, 2023). "Notably, the contradictory associations of WAT IL-1β-secretion with diabetes risk factors in the low-apoB and high-apoB groups cancelled each other when all subjects were combined." (PMID 37914804, 2023). "Importantly, carriers of SORT1 variant with diabetes had larger decreases in plasma apoB, TG, and VLDL and LDL particle number as compared with people without diabetes with the same variants." (PMID 35113816, 2022). "People with diabetes undergo in vivo glycation of LDL apolipoprotein B (Apo B) which gave rise to the hypothesis that lipoprotein glycation contributes to the diabetes and its associated complications." (PMID 35097119, 2022). "ApoB could be incorporated into communicating increased risk for diabetes, in addition to the progression of atherosclerotic disease, especially among high-risk populations." (PMID 35433838, 2022). "Multivariate logistic regression analysis of the Uygur patients showed that ApoB (OR = 11.571, 95% CI: 1.667∼80.340), Gensini score (OR = 1.017, 95% CI: 1.003∼1.031), and history of diabetes (OR = 3.474, 95% CI: 1.189∼10.151) were independent risk factors for ISR in these patients after PCI." (PMID 35958295, 2022). "In a separate MR study, ApoB increased the risk of diabetes after accounting for LDL cholesterol." (PMID 36247924, 2022). "CVD risk factors were hypertension, elevated ApoB:A1 ratio, BMI, diabetes, and smoking." (PMID 36362763, 2022). "Moreover, multiple regression analysis demonstrated that the rs11960458 SNP of AnxA6 was significantly associated with the levels of TC, LDL, and ApoB after adjusting for age, gender, age at disease onset, weight, BMI, arthritis, diabetes, and hypertension." (PMID 36498634, 2022). "ApoB was positively associated with concomitant arthritis, diabetes, and hypertension." (PMID 34996506, 2022). "A large multiethnic cohort study of kidney transplant recipients found that serum ApoB and ApoB/A1 ratio were positively associated with post-transplantation diabetes mellitus with an OR of 12.2 (95%CI: 3.13, 47.5) for ApoB and OR of 8.25 (95%CI: 1.72, 39.5) for ApoB/A1 ratio, respectively." (PMID 33794863, 2021).